PDE4D (phosphodiesterase 4D)
Diseases named in the same sentence as PDE4D in open-access papers (continued):
Sharing a sentence is not in itself a finding about the gene and the disease.
myocardial ischemia (1 paper, 2021). A disorder of cardiac function caused by insufficient blood flow to the muscle tissue of the heart. "PDE4D overexpression largely counteracted miR-370-3p overexpression-mediated protective effects in the myocardial ischemia cell model, suggesting that miR-370-3p protected AC16 cells against hypoxia-induced dysfunction partly by downregulating PDE4D." (PMID 34630853, 2021).
osteoporosis (1 paper, 2005). A condition of reduced bone mass, with decreased cortical thickness and a decrease in the number and size of the trabeculae of cancellous bone (but normal chemical composition), resulting in increased fracture incidence. "After a stepwise selection process an association between an intronic SNP in PDE4D and lumbar spine bone mineral density was detected, providing the first evidence that a variant of this gene could contribute to the risk of osteoporosis in humans." (PMID 15752431, 2005).
pancreatic adenocarcinoma (1 paper, 2023). "Moreover, data obtained from gene expression profiling interactive analysis (GEPIA) show that high PDE4D expression is associated with poor survival of patients with pancreatic adenocarcinoma." (PMID 37427586, 2023). "Analysis of The Cancer Genome Atlas (TCGA) data indicates that PDE4D expression is high in patients with pancreatic adenocarcinoma." (PMID 37427586, 2023).
rectal tumors (1 paper, 2023). "Thus, the newly identified miRNA nov-miR-13844-5p may play a role in CRC by regulating the PDE4D gene, particularly in rectal tumors." (PMID 37987361, 2023).
renal fibrosis (1 paper, 2023). A final common manifestation of a wide variety of chronic kidney diseases characterized by glomerulosclerosis and tubulointerstitial fibrosis. "Thus, PDE4D and TGF-β1 may positively regulate each other as renal fibrosis progresses and mediate liver-kidney crosstalk." (PMID 37072403, 2023).
retinal degeneration (1 paper, 2022). Degeneration of the retina. "Importantly, those regions contained breed-specific genetic markers and candidate genes that are functionally related with pigmentation (e.g. PDE4D), UV protection (e.g. ERCC8), or retinal degeneration (e.g. CWC27, and CLUAP1)." (PMID 36288367, 2022).
Rett syndrome (1 paper, 2023). A severe neurodevelopmental disorder affecting the central nervous system.
skin cancer (1 paper, 2024). "Strong evidence suggests that PDE4D contributes to tumor advancement in lung, central nervous system (CNS), and skin cancers." (PMID 39202484, 2024).
small artery occlusion (1 paper, 2017). "Overall, this study demonstrated that the TT genotype of SNP87 in PDE4D was associated with increased risk of poor outcome after total ischemic stroke, large-artery atherosclerosis and small-artery occlusion, in a Chinese population." (PMID 28225001, 2017).
Tetralogy of Fallot (1 paper, 2024). A congenital cardiac malformation comprising pulmonary stenosis, overriding aorta, ventricular septum defect, and right ventricular hypertrophy. "As for Tetralogy of Fallot, PDE4D (Phosphodiesterase 4D, 600129) is a widely identified heart disease-associated gene signature and has been reported to be associated with different subtypes of CHD in endothelial cells, including Tetralogy of Fallot." (PMID 39202774, 2024). "Using LightGBM, we have already identified PDE4D (Phosphodiesterase 4D, 600129) as a specific gene signature for the Tetralogy of Fallot." (PMID 39202774, 2024).
ulcerative colitis (1 paper, 2020). An inflammatory bowel disease involving the mucosal surface of the large intestine and rectum. "Examples include, SOX9, an important regulator of cell proliferation in the intestinal epithelium and PDE4D, which is known to be associated with ulcerative colitis." (PMID 33308304, 2020).
tumor (47 papers, 2010 to 2026). "PDE4D belongs to the subfamily four of cyclic nucleotide phosphodiesterase and has been implicated in the tumorigenesis of various neoplasms." (PMID 37987361, 2023). "The GNAS p.R201C, c.601C > T variant was observed in the tumor sample of patient #11, and a gene fusion [chr5:58476419(-)::chr2:212615429(-)] showing PDE4D exon 5 fused to ERBB4 exon 5 was observed in the ACT from patient #10." (PMID 32098292, 2020). "Previous studies show that high expression of NR4A2, BTNL9, FOXP1, or PDE4D can antagonize immune response or is associated with tumor progression." (PMID 30911684, 2019). "When applying our diagnostic signature to prostate biopsies, PDE4D isoform expression appeared to return to its ‘normal’ state with increasing distance from the tumour, whereas the tumour edge showed an intermediate signal." (PMID 27683107, 2016). "In HCC, PDE4D interacts with yes-associated protein (YAP) to enhance tumor growth." (PMID 40564004, 2025). "The results showed that overexpression of PDE4D was significantly associated with clinical stage (P = 0.004), T classification (P = 0.003), N classification (P = 0.022), liver metastasis (P = 0.038) and tumor respectability (P=0.017)." (PMID 31772658, 2019). "However, the role of PDE4D in tumor progression is multifaceted, potentially exhibiting both oncogenic and tumor-suppressive activities, which may be associated with the type and stage of the tumor." (PMID 40129976, 2025). "It would therefore be fascinating to further explore in the future whether such a ‘field effect’ indeed influences PDE4D isoform composition, effectively increasing the target area for biopsies, or whether our observations were caused by averaging signals from adjacent tumour and normal cells." (PMID 27683107, 2016). "Our results revealed that synchronized expression of 5-HTR4 and PDE4D proteins represents a stable modulatory signaling axis of glial-tumor biology, and reflects the activity of cAMP signaling pathway, but cannot independently stratify patients." (PMID 41900893, 2026). "Studies found that the PDE4D gene in approximately 20% of prostate tumors, and is closely related to tumor progression." (PMID 40129976, 2025). "Meanwhile, the hydroxymethylation level of PDE4D in the tumour gDNA of the same MLM patients was higher than that in the adjacent tissue." (PMID 39956959, 2025). "Among these genes, PDE4D, LRP1B, CREBBP, and NCOR1 were previously associated with deletions in BC tumor tissue, which favors tumorigenesis or progression." (PMID 40801146, 2025). "In line with the IHC results, PDE4D was significantly overexpressed in tumour tissues compared to normal tissues and exhibited the highest expression in metastatic lesions." (PMID 39956959, 2025). "PDE4D, on the other hand, can alter gene expression and impact the tumor microenvironment, thereby influencing various aspects of cancer biology, including the response to therapies." (PMID 39202484, 2024). "Taken together, these results show that the pharmacological inhibition of PDE4D results in a decreased mTORC1 signaling and tumor growth in vivo." (PMID 37427586, 2023). "The gene expression of the PDE4D transcripts is measured on the extracted RNA from a patient’s tumor sample." (PMID 36612262, 2022). "Although the relationship between these proteins and PDE4D inhibitors has been previously reported for other tumours, our findings represent the first evidence of their specific link with the PDE4D isoform in HCC." (PMID 34062786, 2021). "In these tumour cells, PDE4D is thus required to maintain the cell differentiated state and prevent cancer development." (PMID 31775395, 2019). "(E) The activity of immunoprecipitated PDE4D obtained from tumor tissues of indicated treatment groups." (PMID 30482227, 2018).
tumor (continued). "Notably, roflumilast inhibited the PDE4D/ CCN2 axis and further degraded the phosphorylation of AKT and ERK, which have been reported to be associated with metastases of numerous tumours." (PMID 39956959, 2025). "Furthermore, extensive studies have been conducted to reveal the role of PDE4D in regulating tumor cell growth, angiogenesis, and responses to immune therapy." (PMID 40129976, 2025). "Notably, the expression of PDE4D was validated through RNA sequencing and further confirmed in human CRC tumor samples, indicating a robust association between GNAS mutations and PDE4D overexpression in CRC." (PMID 40564004, 2025). "Additionally, PDE4D has emerged as a novel tumor-promoting molecule, presenting a distinctive targetable enzyme across multiple human cancers, including lung, prostate, melanoma, ovarian, endometrial, and gastric cancers." (PMID 39202484, 2024). "As short PDE4D isoforms are unaffected by autoinhibition and are more active, therefore promoting proliferation of tumor cells, we looked at the two‐dimensional and three‐dimensional growth of A549 cells which have been shown to be sensitive to PDE4D silencing or inhibition." (PMID 39673076, 2024). "Tumor volume and weight were significantly decreased in PDE4D-depleted cells." (PMID 37427586, 2023). "PDE4D is a subtype of metallohydrolases, which is involved in multiple tumor promoting processes." (PMID 36366731, 2023). "Consistently, tumor volume and weight were lower in mice injected with PDE4D inhibitors." (PMID 37427586, 2023). "The DNA damage may be further augmented by the reported downregulation of the PDE4D gene in these tumours." (PMID 37740039, 2023). "Conversely, we found the previously identified PCa driver gene LRP1B (12/17) and new candidate genes TTC28 (16/27), CADM2 (12/16), LSAMP (11/16), EYS (16/18), PTPRD (12/18), PACRG (5/6) and PDE4D (12/17) to be predominately interrupted in tumours from African patients." (PMID 36045381, 2022). "Moreover, the expression of PDE4D in HCC progressively increased with severity of the disease in terms of tumour histological grade." (PMID 34062786, 2021). "Moreover, the in silico gene expression analysis revealed a significant over-expression of the PDE4D transcript in HCC samples compared to non-tumour samples and, of note, higher levels of PDE4D gene expression were an index of poor prognosis." (PMID 34062786, 2021). "In addition, immuno-histochemical staining revealed an overexpression of PDE4D in several different types of primary tumour samples." (PMID 31775395, 2019). "The authors propose that PDE4D may function as a tumour-promoting factor and may represent a unique target for cancer cell therapy." (PMID 31775395, 2019). "PDE4D was mainly localized in the cytoplasm of the PDAC tumor cells." (PMID 31772658, 2019). "Next, the PDE4D expression in tumor tissues was evaluated by western blotting." (PMID 30482227, 2018). "In vivo experiments further demonstrated that the knockdown of PDE4D suppressed tumorigenesis in a NPC murine xenograft model, suggesting that PDE4D may be a tumor-promoting factor in NPC." (PMID 25289091, 2014). "Other genes identified in our screen, such as ALK and PDE4D, increase tumor cell growth and protect from apoptosis, and may therefore promote resistance through these mechanisms." (PMID 23442791, 2013). "We further investigated whether PDE4D knockout could inhibit tumour metastases in vivo." (PMID 39956959, 2025). "Here, however, we have been able to dissect the impact of three different PDE4D transcripts, namely those for the PDE4D5, PDE4D7, and PDE4D9 long isoforms, on the risk of postsurgical disease progression, depending on the genomic background of the patient's tumour." (PMID 31275657, 2019). "In A549 adenocarcinoma cells, the expression of PDE4A and PDE4D increase under hypoxic conditions and enhance HIF signaling, which promotes the proliferation of tumor cells." (PMID 40129976, 2025).
tumor (continued). "High expression of PDE4D correlates with reduced infiltration of CD8+ T cells, suggesting a relative inhibition of the tumor immune microenvironment in LUAD." (PMID 40129976, 2025). "Decreased intracellular levels or inhibition of PDE4D hinders the proliferation of HCC cells, exhibiting tumor-suppressive properties." (PMID 40129976, 2025). "Of all the targets, PDE4D and more significantly, HIF1A showed high expression in ER-negative miR-18a/low tumours." (PMID 38786043, 2024). "PDE4D (phosphodiesterase 4D), a cAMP-hydrolyzing enzyme, has been reported to bind and interact with YAP to enhance tumor progression in HCC." (PMID 39199296, 2024). "In conclusion, our results emphasize the potential clinical utility of PDE4B, PDE4D, and SFRP5, genes that impact tumor initiation, progression, and metastasis, as biomarkers for CRC." (PMID 39202484, 2024). "Gene expression of all three studied genes, PDE4B (p < 0.0001), PDE4D (p < 0.0001), and SFRP5 (p < 0.0001), was significantly lower in tumor tissue in comparison to the control tissue." (PMID 39202484, 2024). "Here, we demonstrated that also PDE4D protein was up-regulated in human HCC tissues and its expression progressively increased with the severity of the tumour." (PMID 34062786, 2021). "Secondary resistant tumor BoC10 showed a strong upregulation of two family members of cAMP-specific phosphodiesterases (PDE4B and PDE4D) of 206 and 15-fold, respectively, compared to the 5-day controls." (PMID 34271981, 2021). "In the present study, we found that the expression of PDE4D was increased in the PDAC samples, compared to their adjacent non-tumor tissues." (PMID 31772658, 2019). "In the present work, we found that PDE4D was up-regulated in the tumor tissue of PDAC at both mRNA and protein level compared with non-tumor tissues." (PMID 31772658, 2019). "The PDE4D expression and TPL2 phosphorylation in T24 tumor tissues were evaluated by immunohistochemistry (IHC)." (PMID 30482227, 2018). "Additionally, a transient change of PDE4D isoform expression at the tumour edge might suggest that nearby adjacent normal tissue is influenced by tumour presence through a ‘field effect’, but could also be due to averaging signals from normal and cancerous cells." (PMID 27683107, 2016). "The relationship between tumor suppression and neural differentiation in GBM has been reported in several studies, however the tumor-suppressive effects of PDE4D inhibitors have rarely been studied." (PMID 24989033, 2014). "Hence, in the present study, firstly we examined the expression of PDE4D in HCC tissues and adjacent liver tissues, and their possible correlation with tumour characteristics." (PMID 34062786, 2021). "Recurrent SVs in CSMD1, WWOX, ERC1, PDE4D and SHANK2 were also identified in five tumor samples." (PMID 32617189, 2020). "PDE4D expression in paired tumor tissues and adjacent noncancerous tissues were detected by western blotting and real time qRT-PCR." (PMID 31772658, 2019). "PDE4D is overexpressed in tumour tissues of patients with MLM but not in those of patients with PC." (PMID 39956959, 2025). "On the other hand, two genes recently proposed to be tumor suppressors based on their focal deletion in cancer, PDE4D and LRP1B, are amongst the top ten most frequently affected CFS-like genes and accordingly may not be functional tumor suppressors." (PMID 23805207, 2013).
cancer (34 papers, 2013 to 2025). A tumor composed of atypical neoplastic, often pleomorphic cells that invade other tissues. "PDE4D has recently been implicated as an oncogene and is correlated with the growth, proliferation and survival of cancer cells 14-16." (PMID 31772658, 2019). "Elevated expression level of PDE4D has been reported to be associated with the proliferation, survival and prognostic in various cancers." (PMID 31772658, 2019). "The suppression of PDE4D by this microRNA results in an increase in the levels of a protein that can cause cancer cells to die." (PMID 27383270, 2016). "However, seldom studies have reported the association of PDE4D with migration, invasion and cancer metastasis." (PMID 31772658, 2019). "Further investigations into the functional implications of PDE4D have revealed that its depletion can induce apoptosis and inhibit growth across multiple cancer cell types, including gastric, breast, lung, and ovarian cancers." (PMID 40564004, 2025). "The expression levels of PDE4A, PDE4B and PDE4D were down-regulated in THCA patients at different cancer stages, while the expression level of PDE4C was significantly up-regulated." (PMID 38514754, 2024). "This cell line was included in a previous study that charted homozygous PDE4D microdeletions that partially or fully removed UCR1/UCR2 regions to elevate PDE4D enzyme activity and promote survival of cancer cells." (PMID 39673076, 2024). "Our analysis identified 2,793 human genes associated with various diseases, including those associated with cancers (such as BRCA1 and BRCA2) and cardiovascular diseases (such as PDE4D)." (PMID 36950105, 2023). "PDE4D silencing/inhibition also affected the gene expression of several cancer-related genes, such as the pro-oncogenic insulin growth factor (IGF2), which is down-regulated." (PMID 34062786, 2021). "The role of PDE4D in HCC was better determined by analysing the PDE4D-dependent expression with an Open Array Real-Time PCR platform of 624 cancer related genes in HepG2 and Huh7 cells silenced for PDE4D or control siRNA (PDE4D-siRNA; Scr-siRNA)." (PMID 34062786, 2021). "Here in this study we provide the first evidence of condition-specific PDE4D promoter switching in a cancer context." (PMID 27683107, 2016). "Further experiments showed that this is because miR-139-5p can suppress the production of a protein called PDE4D, which is often highly expressed in human cancers." (PMID 27383270, 2016). "While our study focused on PDE4D isoform expression in primary PCa samples, genomic alterations of the PDE4D locus such as microdeletions have been observed in other cancers." (PMID 27683107, 2016). "Accordingly, the cancer-preventive and therapeutic effects of several natural products including curcumin and resveratrol were attributed to PDE4D inhibition." (PMID 27602951, 2016). "Analysis of data from large scale genome sequencing projects like TCGA has uncovered a potential role of the PDE4D gene in various types of cancer." (PMID 26575822, 2015). "We showed that mTOR and phosphodiesterase 4D (PDE4D) strongly correlate in resistant EGFR-mutant cancer cell lines." (PMID 26639561, 2015). "Currently the effects of PDE4D in cancer are not fully understood and few studies have examined the role of PDE4D and its inhibitors in cancer therapy." (PMID 26639561, 2015). "It has been reported that PDE4D functions as a proliferation-promoting factor in certain cancer types, including HNC." (PMID 25289091, 2014). "PDE4B and PDE4D have recently been reported as oncogenes in various human cancers." (PMID 39202484, 2024). "First, it promotes cancer cell proliferation and progression by downregulating miR-122a and PDE4D." (PMID 38203269, 2023). "In cancer, focal deletions are often associated with CFS; in a pan-cancer analysis of 4934 cases, 70 recurrent focal deletions were reported, of which 22 were found in large genes and several genes known from CFS regions (FHIT, WWOX, PDE4D, PARK2)." (PMID 35563471, 2022).